MYC (MYC proto-oncogene, bHLH transcription factor)
Diseases named in the same sentence as MYC in open-access papers (continued):
Sharing a sentence is not in itself a finding about the gene and the disease.
tumor (continued). "Our study provides evidence that CREPT and MYC are critical regulators of the malignant transformation of tumor cells." (PMID 39615685, 2024). "NR2F1 overexpression successfully inhibited the proliferation capacity of MMTV-MYC tumor cells obtained from the MMTV-MYC transgenic mouse model characterized by enforced c-MYC expression." (PMID 38418814, 2024). "Silencing of MYC gene in macrophages showed a decrease in tumour angiogenesis and reduction in tumour growth." (PMID 39320855, 2024). "The tumor growth-promoting pathway chaperone-mediated autophagy (CMA) correlates with MYC expression." (PMID 37450923, 2024). "Western blotting revealed that the overexpression of hsa-miR-34a-5 p resulted in a marked downregulation of endogenous MYC protein, emphasizing its significance as a tumor suppressor." (PMID 38791013, 2024). "In conclusion, MYC overexpressing tumor cells mitigated the efficacy of therapeutic antibodies through several non-overlapping mechanisms." (PMID 39596160, 2024). "Research has revealed that tumor cells with high MYC expression exhibit enhanced dependence on CDK1." (PMID 38638876, 2024). "Lactate dehydrogenase (LDH), a metabolic enzyme involved in glycolysis, is regulated by the PI3K/Akt/mTOR pathways, the MYC oncogenic transcription factor, tumor hypoxia, and necrosis." (PMID 39435278, 2024). "These signaling pathways can then directly induce MYC activity and subsequently stimulate the activity of critical nuclear factors that govern tumor migration and invasion, of which the activity of E2F1, CDK4, p27, and p15 stands out." (PMID 38204280, 2024). "High-level activation of oncogenes (e.g., KRAS, BRAF, and c-MYC) triggers intrinsic tumor suppression 46,50–53." (PMID 36778401, 2024). "The median diameter of the largest tumour was 75 mm in patients with MYC amplification and 45 mm in the remaining patients (p = 0.754)." (PMID 38536546, 2024). "CPI-203 and IQS-01.01RS (CXCR4 inhibitor) co-treatment reduced tumor burden by downregulating MYC and p-AKT as well as enhancing apoptosis in DLBCL." (PMID 39580422, 2024). "Certain marine drugs and herb medicines have the potential to modulate MYC activity and inhibit tumor growth." (PMID 37450923, 2024). "Mechanistically, metastatic cell lines recruit MYB via NICD to activate MYC, ultimately promoting tumor migration." (PMID 39263605, 2024). "We found that oncogenic KRAS suppresses interferon signaling within the tumor cells via MYC and down-regulates the antigen presentation machinery and that KRAS-G12C inhibition led to the induction of immunogenic cell death." (PMID 39485838, 2024). "It is possible that increases in either MIROs expression in so many disparate tumor types is—at least in part—from the broad effects of MYC amplifications in these tumors." (PMID 39128718, 2024). "Due to MYC-mediated metabolic reprogramming, tumour cells become dependent on the de novo biosynthesis pathway to sustain cell proliferation, suggesting that these cells are highly sensitive to inhibitors that target this metabolic pathway." (PMID 39766063, 2024). "MYC, as a signature tumor driver, is a critical player in malignant transformation from inflammation to cancer." (PMID 37450923, 2024). "MYC-induced metabolic reprogramming correlates with the emergence of the tumor immune microenvironment." (PMID 37450923, 2024). "The cooperative interplay between RAS and MYC constitutes a complex and multifaceted phenomenon, profoundly influencing tumor development." (PMID 39164274, 2024). "CDC7 inhibition by simurosertib restores proteasome activation and MYC degradation; in a low-MYC state, tumor cells are unable to progress through NE transformation, leading to extended treatment response." (PMID 39054323, 2024).
tumor (continued). "In MYC-driven tumor models, MYC activation and phosphorylation are HMGCR-dependent, leading to a feedback loop that triggers tumorigenesis and cancer metabolic alterations." (PMID 37450923, 2024). "To date, several studies have shown that MYC is one the most commonly altered genes in OS, in which it plays different relevant roles in tumor development and progression, treatment response, and prognosis." (PMID 39596100, 2024). "Second, MYC is critical for preventing tumor eradication by the host immune system and the tumor regression observed in PDAC models upon MYC inactivation depends on an intact immune system." (PMID 38365788, 2024). "Previous studies have confirmed that the overexpression of DLX5 can promote tumor cell growth by directly targeting the c-MYC gene." (PMID 38760791, 2024). "For example, the interaction between CDK4/6 and the transcription factor MYC plays a synergistic role in promoting tumor cell proliferation and metastasis." (PMID 38890443, 2024). "In cancer progression, MYC is essential for angiogenesis, which promotes sprouting of new capillaries from preexisting vessels, to provide factors required for tumor growth." (PMID 37450923, 2024). "For instance, CRISPR-induced MYC gene knockout is considered a potential option to help tumor suppression." (PMID 39281673, 2024). "USP45 (ubiquitin specific peptidase 45) is a de-ubiquitinase for MYC/c-Myc and correlates negatively with the infiltration of NK cells, Th1 cells, macrophages, and dendritic cells into the tumor microenvironment." (PMID 38674024, 2024). "MYC and E2F activation can lead to increased tumor cell proliferation, migration, and invasion, which can contribute to tumor metastasis." (PMID 38358826, 2024). "Administration of MYCi975 significantly reduces MYC-dependent cancer-cell proliferation, expression of MYC target genes, and tumor growth." (PMID 38191557, 2024). "MYC transgenic mice develop prostate PIN/tumor lesions with increasing age, and treatment of the mice with ENZ or abiraterone (ABI) at 4 months of age inhibited prostate growth but CRPC emerged at 7 months of age." (PMID 38115765, 2024). "In the entire 100 cases of DLBCL, 20 cases (20%) displayed MYC-positive tumor cells, and 57 cases (57%) were positive for BCL2 expression." (PMID 39038016, 2024). "In normal cells, transcriptional regulation by c-MYC is highly controlled while being dysregulated in various cancers where it initiates and maintains tumor growth." (PMID 38166947, 2024). "According to previous studies, some compounds that directly or indirectly inhibit MYC have demonstrated anti-cancer activity in preclinical tumor models." (PMID 38573998, 2024). "The highly aggressive behavior of this tumor prompted a more in-depth biological study, which identified overexpression of c-MYC mediated by chromosomal translocation, resulting in a malignant, highly aggressive phenotype." (PMID 38730688, 2024). "Our GSEA suggest that GABRB3 plays varying roles in myogenesis, interferon γ and α responses, and the MYC proto-oncogene pathway during tumor development." (PMID 38287309, 2024). "The data argue that functionally distinct gene sets compete for elongation factors and directly link MYC-driven S-phase progression to tumor immune evasion." (PMID 38365788, 2024). "In contract, IC3 and IC1 groups are more distinguished by proliferative‐related pathways, such as mitotic spindle, E2F targets, and G2M checkpoints, and also by classical tumor pathways including the MYC and Wnt-signaling." (PMID 38971948, 2024).
tumor (continued). "Consistent with the dual BCL2/MYC translocation association with poor patient outcomes, VAL cells showed heightened proliferation in human IL6-conditioned media and caused rapid tumor expansion and early death in the engrafted mice." (PMID 39272864, 2024). "DMG tumour cells often feature higher activity levels of a protein known as MYC, which can contribute to the growth of the tumour." (PMID 39093942, 2024). "It inhibited tumor growth in mice xenografted with MDA-MB-231 cells through PPARβ/δ/c-MYC interaction." (PMID 38667323, 2024). "Conversely, a contrasting negative correlation was identified in pathways governing cellular response to G2M checkpoint, hypoxia, tumor proliferation, MYC targets, DNA repair, and DNA replication." (PMID 39055918, 2024). "In the majority of the studies, MYC is considered positive if = or >40% of tumor cell nuclei are positive." (PMID 39684922, 2024). "MYC:MAX dimerization is a known critical factor for MYC oncogenesis, as demonstrated in Eμ-Myc-driven lymphomagenesis, where MAX loss results in complete abrogation of tumor development." (PMID 38992040, 2024). "High-level activation of oncogenes (e.g. KRAS, BRAF, and c-MYC) triggers intrinsic tumor suppression." (PMID 38921956, 2024). "Tumor DNA from Vk*MYC MM was analyzed using WGS (n = 41) and WES (n = 27), and control tail DNA using WGS (n = 3)." (PMID 38714690, 2024). "Overall, MYC acts as a tumor-initiating gene, influencing cell cycle progression, as well as immune responses, via tumor-intrinsic epigenetic mechanisms." (PMID 37450923, 2024). "Taken together with our results, these findings indicate that aberrant cell cycle activity and malignant proliferation of tumor cells crosstalk between PUSs, E2F, and MYC." (PMID 39162904, 2024). "MYC is a proto-oncogene that codes for a multi-functional transcription factor (cMyc) with a prominent role in tumour cell growth, which has previously been modelled as acting on B cell progression within the cell cycle." (PMID 38965209, 2024). "The presence of supraphysiological concentrations of nucleotide pools imposes an onerous cost on tumor cells to counteract their disastrous damages by intracellular ROS, whose levels are simultaneously augmented upon MYC hyperactivation." (PMID 38493213, 2024). "On the other hand, COPS5 or MYC alone is insufficient to activate genes crucial for tumor growth and invasion fully, indicating their cooperativity is indispensable in cancer development." (PMID 38974382, 2024). "Mounting evidence that MYC plays a central role in tumour initiation, maintenance and progression makes targeting MYC a very attractive strategy for cancer therapy." (PMID 38637125, 2024). "The molecule, A80.2HCl, generated in our study, can degrade MYC when applied at nanomolar concentrations to multiple cancer cells and exhibits a strong inhibitory effect on tumor growth." (PMID 38424044, 2024). "MYC influences the tumour microenvironment to facilitate cancer evasion of host immune surveillance and is a central player in orchestrating cancer growth and immune evasion." (PMID 38637125, 2024). "In conclusion, it was demonstrated that the inhibition of MYC primes the tumor for CD4+-mediated anticancer activities." (PMID 38473324, 2024). "As a powerful transcription factor, MYC plays a vital role in tumor pathogenesis and development, with a wide range of biological activities, including apoptosis, growth, proliferation, differentiation, migration, and cellular metabolism." (PMID 38918775, 2024). "MYC deregulation modulates other immune subsets and stromal cells that participate in the tumor immune evasion." (PMID 39164274, 2024).
tumor (continued). "The EP300–CMTM6–IGF2BP1 axis forms a positive feedback loop to amplify the effect of MYC in tumor stemness, ultimately facilitating PDAC resistance." (PMID 39488785, 2024). "c-Myc (MYC) is a transcription factor (oncogenic) that eases tumor growth partially via metabolic regulation." (PMID 38534215, 2024). "One tumor (case 19) in a 31-year-old female showed a double-hit genotype, which is defined by two chromosome translocations involving MYC and BCL2 and/or BCL6 rearrangements." (PMID 38730692, 2024). "FBXW7 plays a pivotal role as a tumor suppressor by orchestrating the proteasome-driven degradation of oncoproteins, including but not limited to c-MYC, MCL1, Notch1/4, cyclin E and mTOR." (PMID 38444581, 2024). "In normal cells, glutamine is rarely used to provide energy, whereas tumor cells induce metabolic reprogramming of glutamine via Kras and MYC, leading to glutamine addiction in cancer." (PMID 38521793, 2024). "Inhibition of WEE1 promotes the immune response via the STING-TBK1-IRF3 pathway, enhances the antitumor effect of PD-L1 antibodies through the STAT1 pathway, and significantly suppresses tumor progression in SCLC models (including MYC-stabilized SCLC)." (PMID 39103941, 2024). "In cancers defined by overexpression or dysregulation of the MYC oncogene this process becomes impaired, leading to genomic instability and tumor evolution." (PMID 38605297, 2024). "Investigation of the biochemical crosstalk between c-MYC and mTOR pathways during tumor development has shown that mTORC2/AKT1 is required for c-MYC–driven HCC." (PMID 39325536, 2024). "1C8 and GPS167 impacted the expression and splicing of transcripts in pathways relevant to tumor progression, including MYC targets and the epithelial mesenchymal transition (EMT)." (PMID 38753413, 2024). "These MYC-dependent transcriptional activations contribute to shaping the gene expression profiles that are essential for tumor initiation and growth." (PMID 39456601, 2024). "Correlation analysis revealed a significant correlation of AURKA, AURKB, BUB1, HJURP, TOP2A, and TTK with tumor proliferation, G2M checkpoint, MYC targets, and DNA replication." (PMID 38726001, 2024). "All these data support that NUDT1 expression is required to sustain tumor cell survival in both mouse and human cancers that rely on MYC(N) hyperactivation." (PMID 38493213, 2024). "The c-MYC/pCMV–injected mice developed a lethal tumor burden and were euthanized within 8.9–13.0 weeks after injection." (PMID 39325536, 2024). "The effects of castration on MYC expression matched its effects on tumor growth, decreasing MYC expression in Rv1-WT and, to a lesser extent, in dKO-19, but not in castration-resistant Rv1-Luc." (PMID 38546787, 2024). "To gain more insight into this, we used synthetic MYC inhibitor 10058-F4 in a relatively broad panel of MYC overexpressing cell lines and primary tumor cells from B-cell malignancies, including DLBCL, BL and MM." (PMID 39596160, 2024). "MYC, a pivotal regulatory gene in tumorigenesis, exhibits significantly elevated expression levels in various tumor types." (PMID 39430761, 2024). "The Vk*MYC model replicates the human disease in many ways, including the role of T cells for tumor control." (PMID 38351079, 2024). "Downregulated c-MYC expression is consistent with tumor growth suppression on blocking of the CCL2/CCR2 axis, which is a potential target for patients with hepatocellular carcinoma and chronic hepatic inflammation." (PMID 37450923, 2024). "Depletion of RBBP6 or CPSF3 resulted in 3’US of the ceRNA of the OG MYC, thereby reducing MYC expression and leading to inhibition of tumor growth." (PMID 38503731, 2024). "Conversely, high ACLY expression was negatively correlated with the G2M checkpoint, MYC targets, and E2F targets, indicating an inverse relationship with cancer proliferation and anti-tumor immunity." (PMID 39399493, 2024).
tumor (continued). "We discovered that injection of c-MYC/MCL1/Cre into Rictorfl/flTsc2fl/fl mice induced a lethal tumor burden within 1.7–4.0 weeks after injection, whereas in control mice, a fatal tumor burden occurred 4.1–8.7 weeks after injection." (PMID 39325536, 2024). "Our results indicate that stromal FOXC1 and tumor pERK1‐2 expression provide stronger prognostic value compared to established factors, including cell of origin and MYC/BCL2 double expression." (PMID 39404228, 2024). "MYC inhibition has been shown to reduce ATRT tumor growth in vivo and employ the BET inhibitor; IQ1 in orthotopic ATRT xenografts has mimicked the effect of direct MYC inhibition." (PMID 39125735, 2024). "Immunohistochemical staining of sections from tumor xenograft models demonstrated reduced protein levels of PRMT1 and c-MYC in tumor xenografts derived from TRIM25-knockdown GBM#021 cells relative to controls." (PMID 38303029, 2024). "The overexpression of SIRT3 inhibits Akt phosphorylation, leading to the degradation of the oncoprotein c-MYC via ubiquitination, which is crucial for tumor suppression." (PMID 39796040, 2024). "In selected cases enrichment of cancer gene mutations, such as copy number gain of MYC and KRAS, and pathogenic variants of IDH1 and STK11, was observed in residual tumor cells following study therapy." (PMID 38689060, 2024). "Multivariable Cox proportional hazards model of stromal cell FOXC1 and tumor cell pERK1‐2 expression, NCCN‐IPI risk group, cell of origin, and MYC/BCL2 double expression in DLBCL patients (n = 92)." (PMID 39404228, 2024). "In this context, restoring MIRO2 expression in MYC-depleted cells led to rescue of cortical mitochondria and PCa tumor cell motility and invasion." (PMID 39128718, 2024). "MYC represses miR-34a and let-7 to accelerate the tumor by binding respective miRNA promoters as well." (PMID 38561330, 2024). "H&E- and HA-stained liver sections confirmed tumor formation and HA-tagged MYC and CTNNB1 expression in tumors." (PMID 39353892, 2024). "BL is the first example of a virus-associated human neoplasm, being strictly associated with Epstein Barr virus (EBV), and shows the activation of the MYC oncogene." (PMID 39684922, 2024). "The authors established that MYC overactivation led to a decrease in immune cell infiltration of the tumor mass, particularly referring to the macrophage population." (PMID 39596100, 2024). "The phosphoinositide−3−kinase/AKT/mTOR signaling pathway is critical to tumor development and metastasis and important in MYC regulation." (PMID 38785546, 2024). "Next, we wanted to find out which MYC effector proteins are highly expressed in PDAC tumours with high MYC activity, but show low expression in tumours with low MYC levels and in normal tissue." (PMID 38821858, 2024). "Gross images and histological analysis showed that c-MYC/FOXO1AAA mice had tumor burdens and histology similar to those of the control group." (PMID 39325536, 2024). "MYC‐ON mice were switched to a normal diet to induce tumor formation at the age of 6 weeks and then treated with DMSO, DU101, or DU102 at the dose of 5 mg kg−1 by gavage for 6 weeks." (PMID 39225354, 2024). "By competitively binding to miR-204, lncRNA MALAT1 upregulates IGF2BP2 via m6A modification and enhances MYC expression, thereby stimulating the proliferation, migration, and invasion of TC cells, accompanied by the attenuation of tumor growth and apoptosis." (PMID 39403369, 2024).